IL17D (interleukin 17D)
Description:
Induces expression of IL6, CXCL8/IL8, and CSF2/GM-CSF from endothelial cells.
Synonyms: IL-17D; IL-27; IL27; FLJ30846
Tractability: Antibody: UniProt places it where antibodies can reach, with medium confidence; UniProt predicts a signal peptide or a membrane-spanning region; its Gene Ontology location is reachable by antibodies, with medium confidence.
Gene: Protein-coding gene on chromosome 13 (20,702,127 to 20,723,099, forward strand). Ensembl gene ENSG00000172458.
Subcellular location: Secreted
Gene Ontology:
Molecular function: cytokine activity; protein homodimerization activity; receptor ligand activity
Biological process: inflammatory response; negative regulation of hemopoiesis; positive regulation of cytokine production involved in inflammatory response; positive regulation of granulocyte macrophage colony-stimulating factor production; positive regulation of interleukin-6 production; positive regulation of interleukin-8 production; signal transduction
Cellular component: extracellular region
Genetic constraint (gnomAD): Loss-of-function variants: 13 observed, 4.96 expected, observed/expected ratio (o/e) 2.62. That is too few expected variants to judge how well the gene tolerates losing a copy. Missense variants: 353 observed, 234.07 expected, observed/expected ratio (o/e) 1.51, 90% interval 1.38 to 1.65. Synonymous variants: 172 observed, 115.2 expected, observed/expected ratio (o/e) 1.49, 90% interval 1.32 to 1.69.
Homologues: Orthologues: chimpanzee IL17D (100% identical), macaque IL17D (99% identical), guinea pig IL17D (86% identical), mouse Il17d (85% identical), rat Il17d (84% identical), pig IL17D (77% identical), dog IL17D (76% identical), tropical clawed frog il17d (63% identical), zebrafish il17d (55% identical). Paralogues in human: IL17C (24% identical), IL17B (21% identical), IL17A (19% identical), IL17F (19% identical), IL25 (19% identical).
Diseases named in the same sentence as IL17D in open-access papers:
IL17D is named in the same sentence as 51 diseases in open-access papers, as found by Europe PMC text mining. Sharing a sentence is not in itself a finding about the gene and the disease. The quoted sentences say what the papers report.
viral infections (10 papers, 2018 to 2024). "IL-17D is required for optimal antiviral immunity as well: also in this case, viral infection induces Nrf2 and IL-17D, causing local oxidative stress and antiviral responses." (PMID 33244315, 2020). "The same group also showed that mice deficient for IL-17D are more susceptible to viral infections and tumors." (PMID 33244315, 2020). "Of note, we also observed that Il17d−/− mice were partially resistant to influenza infection on the basis of a weight loss difference, suggesting that IL-17D is a pathogenic molecule during acute virus infection." (PMID 31244826, 2019). "In addition, IL-17D plays a role in the control of viral infections and cancer, as IL-17D deficiency predisposes animals to these conditions." (PMID 30127781, 2018). "IL-17D, on the other hand, increases during tumors and viral infections, stimulating endothelial cells to trigger classical pro-inflammatory cytokine responses." (PMID 38396502, 2024). "Due to a greater tumor incidence and worsened viral infections in il17d-/- mice compared to wild-type (WT) animals, it is clear that IL-17D expression in tumors and virally infected cells is crucial for optimum protection of the host." (PMID 37946175, 2023). "Not only was Nrf2 activated in primary tumors, but IL-17D was also following viral infection in vivo." (PMID 37946175, 2023). "Compared to wild-type animals, IL-17D(−/−) mice showed a higher incidence of cancer and exacerbated viral infections, indicating that the expression of IL-17D after viral infection and tumors is essential for the protection of the host." (PMID 33132897, 2020). "Together, our data led to the identification of IL-17D as a critical cytokine during intracellular bacteria and virus infection that suppresses the activity of CD8 T cells by regulating dendritic cells." (PMID 31244826, 2019). "Our results implicate the Nrf2/IL-17D axis as a sensor of viral infection and suggest therapeutic benefit in boosting this pathway to promote innate antiviral responses." (PMID 30209334, 2018). "Expression of IL-17D in tumors and virally infected cells is essential for optimal protection of the host as il17d(−/−) mice experienced a higher incidence of tumors and exacerbated viral infections compared to WT animals." (PMID 29548303, 2018). "In addition, IL-17D has been found to increase in tumors and during viral infections where Nrf2-mediated IL-17D expression plays an important role in the antitumor as well as the antiviral response through the regulation of innate immune cell recruitment." (PMID 38068860, 2023). "Nrf2 and IL-17D are produced by viral infection, most likely as a result of local OS." (PMID 37946175, 2023). "Also, Nrf2 induces tissue repair genes, anti-oxidative protein, CD36 as scavenger receptor, and IL-17D as protector against viral infections." (PMID 33743807, 2021). "IL-17D has some effect during inflammation, tumors, and viral infection." (PMID 33132897, 2020).
psoriasis (9 papers, 2015 to 2025). An autoimmune condition characterized by red, well-delineated plaques with silvery scales that are usually on the extensor surfaces and scalp. "Furthermore, studies have implicated the IL-17D signaling pathway in the pathogenesis of skin inflammation (e.g., psoriasis), neurological inflammation and cardiovascular inflammation." (PMID 40943530, 2025). "Compared to IL-17A, IL-17F, and IL-17A/F heterodimers, IL-17B, IL 17C, IL-17D, and IL-17E are less characterized in the context of psoriasis." (PMID 40243580, 2025). "Subsequently, we will summarize the current knowledge around IL-17A and its five currently known homologues, namely IL-17B, IL-17C, IL-17D, IL-17E (also known as IL-25) and IL-17F, in relation to psoriasis with a focus on the most recent discoveries." (PMID 37283755, 2023). "In this review, we will summarize the current knowledge around IL-17A and its five currently known homologues, namely IL-17B, IL-17C, IL-17D, IL-17E (also known as IL-25) and IL-17F, in relation to skin inflammation in general and psoriasis in particular." (PMID 37283755, 2023). "Similar to IL-17B, studies addressing IL-17D in psoriasis are scarce, but there is limited evidence of decreased levels in psoriatic skin lesions." (PMID 34201664, 2021). "Expression arrays have shown that IL-17D is suppressed in human psoriasis samples and several types of human tumors." (PMID 31244826, 2019). "However, a differential role of IL-17B, IL-17C, IL-17D and IL-17E has been given during inflammation and, overall, in psoriasis." (PMID 40243580, 2025). "Therefore, the cells that express IL-17D in AD and psoriasis remain to be determined." (PMID 36271146, 2022). "The role of IL-17D, not only in psoriasis but also in inflammatory diseases, is largely unknown." (PMID 34201664, 2021). "We did not observe IL-17D expression in skin adipocytes and keratinocytes during AD and psoriasis." (PMID 36271146, 2022). "Similarly, we show that also neutrophils isolated from patients with active psoriasis do not express IL-17F, IL-17B, IL-17C, IL-17D, and IL-17E as well as IL-17RC mRNA when activated by R848, IFNγ plus LPS, and IL-17A in vitro." (PMID 29719541, 2018). "In psoriasis, IL-17RA plays a key role in pathogenesis based on: (a) IL-17A, IL-17F, and other IL-17 isoforms are involved in disease development; and (b) IL-17RA is essential for signaling of all IL-17 cytokines but IL-17D, whose receptor has not been identified to date." (PMID 34201664, 2021).
lung carcinoma (5 papers, 2022 to 2026). "In this study, we found that aberrantly-expressed IL-17D was associated with lung cancer development and progression." (PMID 35939336, 2022). "In this study, we found that IL-17D was highly expressed in human lung cancer, and increased IL-17D expression was associated with tumor stage and short overall survival." (PMID 35939336, 2022). "We found that IL-17D was highly expressed in lung cancer and associated with poor clinical outcomes." (PMID 35939336, 2022). "IL-17D expression is considerably lower in lung cancer and is associated with improved survival." (PMID 37816755, 2023). "In lung cancer cells overexpressing IL-17D, upregulation of chemokine (C–C motif) ligand (CCL) 3/4 and colony stimulating factor 1 has been observed." (PMID 40536951, 2026). "In lung cancer, IL-17D enhances tumor progression by recruiting macrophages to the tumor site and activating the p38 MAPK signaling pathway, promoting macrophage polarization." (PMID 40536951, 2026). "More research on the relationship between IL-17D and lung cancer progression is required in order to identify effective lung cancer therapy targets." (PMID 37816755, 2023). "To evaluate the function of IL-17D in lung cancer, we overexpressed IL-17D in the human lung carcinoma cell line A549 and mouse lung carcinoma cell line LLC1, which do not express endogenous IL-17D." (PMID 35939336, 2022). "Our study indicated that IL-17D overexpression in subcutaneous tumor model of lung cancer exhibited a similar level of NK cells as control tumor." (PMID 35939336, 2022). "We found that CCL3, CCL4, and CSF1 were significantly upregulated in IL17D–expressing human lung cancer cells, whereas Ccl3, Ccl4, and Il6 were induced in IL17D–expressing murine lung cancer cells." (PMID 35939336, 2022). "To investigate the role of IL-17D in the immune microenvironment of lung cancer, we used flow cytometry to characterize the tumor-infiltrating immune cells in a subcutaneous tumor model of IL17D–expressing LLC1 cells." (PMID 35939336, 2022). "High expression of IL-17D in lung cancer cells activates p38 MAPK signaling pathway through binding to receptor complexes of lung cancer cells." (PMID 35939336, 2022). "The expression of genes related to TAM recruitment and polarization is significantly upregulated in the lung cancer cells with high expression of IL-17D, which finally promotes TAM infiltration." (PMID 35939336, 2022). "The mRNA expression of CCL3, CCL4, and CSF1 was significantly upregulated in IL17D–expressing A549 cells compared with that in control cells, whereas IL17D overexpression in the murine lung cancer cell line LLC1 increased Ccl3, Ccl4, and Il6 expression." (PMID 35939336, 2022). "Quantification of staining based on the intensity of IL-17D staining and the percentage of IL-17D-positive lung cancer cells revealed higher expression of IL-17D in SCLCs than in NSCLCs." (PMID 35939336, 2022). "Similarly, IL-17D in lung cancer facilitates immune evasion by enhancing macrophage recruitment to the tumor site via the p38 MAPK signaling pathway." (PMID 40536951, 2026). "Targeting IL-17D may offer a valuable strategy to counter immune escape and improve therapeutic outcomes in patients with lung cancer." (PMID 40536951, 2026). "IL-17D is another cytokine that facilitates the infiltration of TAM in lung cancer cells." (PMID 38983267, 2024). "Many IL-17D-positive lung cancer cells exhibited cytoplasmic localization." (PMID 35939336, 2022). "Subsequently, we performed immunohistochemical staining to study IL-17D expression in human lung cancer tissues, including 197 NSCLCs (50 squamous cell carcinomas, 124 adenocarcinomas, 12 adenosquamous carcinomas and 11 large cell carcinomas), 13 SCLCs and 68 normal lung tissues." (PMID 35939336, 2022). "Here, we study the molecular and clinical consequences of IL-17D expression in lung cancer." (PMID 35939336, 2022).
lung carcinoma (continued). "Among these differently expressed genes, IL-17D gene, whose function in lung cancer is unknown, was upregulated in NSCLC and SCLC compared with that in normal airway epithelial cells." (PMID 35939336, 2022). "To assess whether IL-17D promotes TAM infiltration by inducing p38 MAPK activity in lung cancer, we first examined the effect of a p38 MAPK inhibitor on the expression of genes related to TAM recruitment and polarization." (PMID 35939336, 2022). "These suggest that IL-17D might regulates lung cancer cells producing cytokines through CD93 on lung cancer cells, which indirectly leads to TAM infiltration." (PMID 35939336, 2022). "We tested the effect of IL-17D expression on the invasion and migration of lung cancer cells." (PMID 35939336, 2022). "Among lung cancer (including NSCLC and SCLC), a lower CTL level indicates better patient survival, but only when IL-17D has a high expression level (p < 0.05)." (PMID 36159856, 2022). "However, the role of IL-17D in the progression of lung cancer remains unclear." (PMID 35939336, 2022). "IL-17D is a novel cytokine of the IL-17 family of cytokines whose function in lung cancer has not been elucidated." (PMID 35939336, 2022). "In the current study, IL-17D overexpression in lung cancer cells did not affect ERK activation, which is consistent with the lack of change in cell proliferation between IL-17D–expressing lung cancer and control cells." (PMID 35939336, 2022). "Our study provides a rationale for understanding the function of IL-17D in tumor progression and suggests that targeting IL-17D and blocking p38 MAPK activity may be a new strategy for the treatment of lung cancer." (PMID 35939336, 2022). "We also analyzed single cell RNA-seq data of 42 NSCLC samples in NCBI GEO dataset GSE148071, and found that IL-17D was mainly expressed in lung cancer cells, while lowly expressed or not expressed in fibroblasts, alveolar cells, normal epithelial cells and immune cells." (PMID 35939336, 2022). "To evaluate the correlation between IL-17D and the activation of the p38 MAPK signaling pathway in individual primary lung cancer tissues, we used immunohistochemistry to study the expression levels of IL-17D and phosphorylated p38 (p-p38) in serial sections of lung cancer samples." (PMID 35939336, 2022). "IL-17D promoted primary tumor growth in a subcutaneous tumor model, whereas it did not affect lung cancer cell proliferation in vitro, indicating that IL-17D might promote tumorigenesis by influencing the tumor immune microenvironment." (PMID 35939336, 2022).
breast carcinoma (4 papers, 2018 to 2022). "The expression levels of IL-17B and IL-17D in breast cancer were quantitatively analyzed because they showed much higher expression than other cytokines from the IL-17 family." (PMID 33102239, 2020).
ovarian carcinoma (4 papers, 2018 to 2025). A malignant neoplasm originating from the surface ovarian epithelium. "The transcripts, in particular WFDC1 and IL-17D, encode secreting factors that not only limit the metastasis of ovarian cancer, but also remodel the tumor immune microenvironment towards tumor suppression." (PMID 29548303, 2018). "Immunohistochemistry analysis revealed that in ovarian cancer specimens with high SORBS2 expression, expression of WFDC1 and IL-17D was also reduced in both primary and metastatic foci of ovarian cancer." (PMID 29548303, 2018). "Given that SORBS2 knockdown reduced the stability and subsequent abundance of WFDC1 and IL-17D transcripts, we attempted to characterize the functional roles of these two genes in metastatic colonization of ovarian cancer cells." (PMID 29548303, 2018). "Results showed that the expression of WFDC1 (P = 0.0016, hazard ratio (HR) = 0.66 (0.51–0.86)) and IL-17D (P = 0.019, HR = 0.7(0.52–0.95)) was positively correlated with overall survival of ovarian cancer patients in TCGA dataset." (PMID 29548303, 2018). "As WFDC1 and IL-17D are secreted factors and are reported to be immunomodulatory, we further focused on the immunomodulatory role of these two genes in ovarian cancer metastasis." (PMID 29548303, 2018). "SORBS2 enhanced the stability of WFDC1 and IL‐17D and inhibited the invasion in ovarian cancer." (PMID 34890108, 2022). "In detail, reconstituting the expression of either WFDC1 or IL-17D or a combination of both in SORBS2-knockdown ovarian cancer cells significantly reduced the number of metastatic nodules and ascites volume compared with control SORBS2-knockdown ovarian cancer cells in vivo." (PMID 29548303, 2018). "In addition, in the Gilks cohort (GSE3208), the expression of IL-17D was significantly lower in stage I and II ovarian cancer patients compared with stage III and IV ovarian cancer patients (P = 0.023)." (PMID 29548303, 2018). "Our study demonstrated that forced expression of IL-17D in SORBS2-depleted ovarian cancer cells could also significantly reduce ovarian cancer metastatic colonization." (PMID 29548303, 2018). "Moreover, the in vivo metastatic colonization potential of SORBS2-depleted ovarian cancer cells was also remarkably reduced after overexpression of either WFDC1 or IL-17D or a combination of them." (PMID 29548303, 2018). "Moreover, we examined the relative concentrations of WFDC1 and IL-17D in the ascites of ovarian cancer patients in low and high SORBS2 tissues." (PMID 29548303, 2018). "As WFDC1 and IL-17D are secreted factors released by SORBS2-low ovarian cancer cells, we wondered whether they have any impact on the tumor microenvironment upon ovarian cancer metastasis." (PMID 29548303, 2018). "Thus, SORBS2-bound transcripts of WFDC1 and IL-17D served as potent metastatic suppressors in ovarian cancer." (PMID 29548303, 2018). "Moreover, in an immuno-proficient model, we also found that WFDC1 and IL-17D could potently suppress ovarian cancer metastasis and are able to inhibit the accumulation of tumor-promoting myeloid cells." (PMID 29548303, 2018). "ITLN1, conversely, antagonizes tumor neovascularization and MDSC accumulation via IL-17D/CXCL2 axis modulation, thereby reshaping the immunosuppressive TME—a mechanism aligning with its prognostic significance in both CRC and ovarian cancer." (PMID 40145096, 2025). "Our study shows that supernatants of both WFDC1- and IL-17D-overexpressed, SORBS2-depleted ovarian cancer cells significantly reduced the amount of HLA-DRlo/neg CD14+ cells in vitro." (PMID 29548303, 2018). "The steady-state levels of these seven transcripts were assessed in two SORBS2-knockdown ovarian cancer cell lines and we identified the mRNAs of two genes, WFDC1 and IL-17D, as exhibiting reduced steady-state levels upon SORBS2 knockdown in both cell lines." (PMID 29548303, 2018).
ovarian carcinoma (continued). "However, conditioned media from either WFDC1 or IL-17D overexpressed, SORBS2-depleted ovarian cancer cells significantly reduced the amount of HLA-DRlo/neg CD14+ cells." (PMID 29548303, 2018). "We observed that stable overexpression of either WFDC1 or IL-17D or a combination of both significantly decreased the invasive capacity of SORBS2-depleted ovarian cancer cells compared with control, revealed by Transwell chamber analysis and wound healing analysis." (PMID 29548303, 2018).
COVID-19 (3 papers, 2022 to 2025). A disease caused by infection with severe acute respiratory syndrome coronavirus 2. "Overall, these results have identified an association between two cytokines of the IL-17 family (IL-17D and IL-17F) with COVID-19 and disease severity." (PMID 39493750, 2024). "A previous study showed that the systemic concentrations of neutrophil chemokines (CXCL1/8), myeloperoxidase levels, and nasal IL17D transcription are correlated with the functional severity of COVID-19." (PMID 40362649, 2025). "Moreover, increased plasma levels of IL-17D, IL-17E and IL-17F were noted when comparing severe versus mild COVID-19." (PMID 39493750, 2024). "Several mediators such as Tie-2, VEGFA, IL-17D, IL-3, GM-CSF, IL-1α, IL-5, Eotaxin 3, IL-12p70 and IL-13 were not significantly different between COVID-19 and control subjects (data not shown)." (PMID 36116160, 2022).